MMP14 (matrix metallopeptidase 14)
Diseases named in the same sentence as MMP14 in open-access papers (continued):
Sharing a sentence is not in itself a finding about the gene and the disease.
cancer (continued). "We also observed an increased expression of some metalloproteinases such as MMP14 and MMP2, which are known mediators of cancer invasion and a remarkable decrease of two metalloproteinases, MMP11 and MMP12, which are known to have a protective role against tumors." (PMID 34680461, 2021). "The MMP-14 promoter also has a binding site for the repressing transcription factor PROX1 upstream of the main transcription start site, which significantly affects the invasiveness of cancer cells by downregulating MMP-14." (PMID 35008569, 2021). "Matrix metalloproteinase 14 (MMP14), which through its ECM-degrading effect promotes cancer cell migration, was expressed at significantly different levels by cancer cells in the four patterns: highest in FP (58%), followed by CP (20%) and PP (13%), and TP (2%) (p ≤ 0.037), respectively." (PMID 33672734, 2021). "Among these proteins, the overexpression of MMP14, ITGA2, THBS2, COL1A1, COL3A1, COL11A1 and COL6A3 has been experimentally confirmed in PDAC, while that of COL12A1 and COL5A2 has been shown in other types of cancer." (PMID 34094925, 2021). "Furthermore, this increased expression of several MMPs, including MMP-9, MMP-2, and MT1-MMP (i.e. MMP-14), are secreted by a variety of metastatic cancer cells to aid in ECM degradation." (PMID 32829709, 2020). "Total content of MMP-14, MMP-15, and TIMP-1 in control human urinary bladder and its cancers." (PMID 32049862, 2020). "After confirming the expression of the TRAIL construct under the UBC promoter and the sensitivity of PyMT cancer cells to the TRAIL in vitro, the TRAIL was placed under the MMP14 promoter fragment in a lentiviral vector and was used for in vivo efficacy study in the intracranial PyMT model." (PMID 31501884, 2020). "Among these proteases, a transmembrane MMP, MMP-14 (MT1-MMP), has been shown to be a master regulator of invadosome function and to cleave and activate pro-MMP-2, which is transported to the forming invadosomes during cancer cell invasion." (PMID 30818851, 2019). "In addition, many activated or cancer cell types, including HT1080 fibrosarcoma cells, express a range of matrix metalloproteinases (MMPs) such as MMP-14." (PMID 31431171, 2019). "In cancer cells, mature invadopodia are enriched in MMP2, MMP9, and MMP14." (PMID 30356678, 2018). "However, it appears that MMPs are important enzymes involved in local attack and metastatic PTC cancer, being reported in several studies related to different members of the MMP family, including MMP-1, MMP-2, MMP-7, MMP-9, MMP-10, MMP-13, MMP-14 and MMP-15." (PMID 30509240, 2018). "For patients with an intestinal type of cancer, 5-year survival reached 64.1% (95% CI 58.2–70.0) among those with a low serum MMP-14 and 13.3% (95% CI 1.0–25.6; p = 0.002) among patients with a high serum MMP-14." (PMID 30532247, 2018). "Interestingly, MT-MMPs (MMP-14 and MMP-16) have been reported to play pivotal roles in cancer cell migration and metastasis." (PMID 29643421, 2018). "Besides COL1A1, serpin family E member 1 (SERPINE1), matrix metallopeptidase 9 (MMP-9) and matrix metallopeptidase 14 (MMP-14), were all drastically increased in cancer lesions as well." (PMID 29720137, 2018). "MMP14, a membrane-type matrix metalloproteinase (MMP), promotes cancer invasion and metastasis." (PMID 28367998, 2017). "Notably, MMP14 is ‐ together with AXL, caveolin 1 (CAV1) and ITGA5 ‐ among the top genes contributing to the differentiation of cancer from normal tissue." (PMID 28596300, 2017). "MMP14 proteolytic activity is involved in directly activating MMP2, and indirectly activating MMP13 and MMP9, leading to enhanced cellular invasiveness, especially in cancer metastasis." (PMID 27478693, 2016). "Alternatively, different cancers might preferentially use either the MMP2 and MMP9, or MMP14 targeting pathways." (PMID 27789576, 2016). "Membrane-bound MMP-14 is required to activate MMP-2 and is known to be involved in cancer invasion." (PMID 24959847, 2014).
cancer (continued). "Another interesting pathways activated in both cancer cell lines is the extracellular matrix organization which involves up-regulation of different collagen genes like (COL1A1, COL1A2, COL3A1), and matrix metallopeptidase like (MMP8, MMP14)." (PMID 25077705, 2014). "Similarly, E-cadherin has been reported to transcriptionally regulate a variety of integrins and matrix metalloproteases (MMP1, MMP2, MMP3, MMP14 and TIMP-1) in other cancer models." (PMID 19257890, 2009). "MMP-2 and MMP-14 expression by cancer cells was not evaluated because too few cases expressed those markers." (PMID 16776850, 2006). "Finally, histological characterization of tissue specimens from patients with grade 3, stage III-IV CRC identified high MMP14 expression localized to cancer lesions and not adjacent colon tissue." (PMID 38329810, 2024). "Some downregulated genes (EHF and MMP14), mainly involved in proliferation and cancer development, were not restored upon EZH2 inhibitor treatment, and some that were upregulated in KO samples retained or even increased their high expression after treatment (EFCAB6 and CDKN2A)." (PMID 38672463, 2024). "However, to date, the usefulness of specific MMP14 inhibitors in cancer treatment has not been demonstrated clinically, and the failure of previous clinical trials has been partly attributed to the inhibition of antitumour functions of MMP14." (PMID 37078535, 2024). "However, ZO-2 inhibited the MMP14 expression and suppressed ability of cell invasion, suggesting the non-redundant functions of ZO-1 and ZO-2 in cancer cells." (PMID 37564207, 2023). "Additionally, detection of markers for the cancer-associated fibroblasts, S100A4/Fsp-1, and α-SMA indicated that ablation of MMP14 in fibroblasts does not reduce the amounts of these cells around tumors." (PMID 33924099, 2021). "However, the regulation of the expression and activity of MMP-14 by collagen-binding integrins and how the topography and biomechanical properties of supramolecular collagen affect MMP-14-dependent cancer cell invasion are still not completely understood." (PMID 35008569, 2021). "Interestingly, MMP-14 has been proposed as an activator of latent MMP-2 in conjunction with tissue inhibitors of metalloproteinase 2 (TIMP-2) for degradation of extracellular matrix and promotion of cancer invasion and metastasis." (PMID 32848608, 2020). "Moreover, MMP14 expression in cancer cells induces the expression of MMP14 in blood but not in lymphatic endothelial cells." (PMID 31466240, 2019). "This supports the prominent role played by MMP14 in cancer metastasis indicating that a low or absent PROX1 expression may be required for MMP14 to be highly expressed." (PMID 31560170, 2019). "In addition to a 94% suppression of metastasis to the lungs and livers of animals treated with the mAb, we found higher expression of MMP-14 by cancer stem cells and evidence that MMP-14 contributes to the ability of cancer stem cells to initiate a metastatic colony." (PMID 30034628, 2018). "A stimulatory effect of MMP-14 on cell proliferation has been shown to be mediated through its hemopexin domain, but whether a similar effect of MMP-14 occurs in cancer stem cells has not been previously addressed." (PMID 30034628, 2018). "Furthermore, high TIMP-2 expression by cancer cells was present in 225 (41.7%) cases while cancer cells expressed MMP-14 in 4 (0.7%) cases and none expressed MMP-2." (PMID 16776850, 2006). "Membrane-type matrix metalloproteinase 1 (MT1-MMP), also known as MMP-14, is a membrane-bound collagenase that has been shown to localize to the leading edge of invading cells, degrade surrounding extracellular matrix, and play a pivotal role in cancer cell dissemination." (PMID 17156449, 2006).
cancer (continued). "We had previously identified and validated HSP90 as one antigen for patient autoantibodies through a stringent biochemical approach; this does not, however, rule out the possibility that HSP90 and MMP14, among other MMPs, may all represent accessible anti‐cancer drug targets." (PMID 40985572, 2025). "However, there has been a lack of relevant reports on the effect of MMP14 across cancers." (PMID 34604053, 2021). "miR-484 is a key factor in cancer and non-cancerous diseases, and its targets in cancer include VEGFB, VEGFR2, MAP2, MMP14, HNF1A, TUSC5, and KLF12." (PMID 36572856, 2022). "Autocatalytic and non-autocatalytic shedding of the MMP-14 ectodomain from the cell surface yielding either catalytically inactive fragments or soluble catalytically active ectodomains also seems to be a way to regulate its activity and may be important in cancer progression." (PMID 33379400, 2020). "Moreover, MMP14 expression seems to be higher in NSCLC tissues than noncancerous mucosa, which suggests that cancer patients with high MMP14 expressions have an unfavorable prognosis than those with low MMP14 expressions." (PMID 34868395, 2021). "There are now some selective MMP inhibitors developed for the treatment of the non-neoplastic disorders and cancer, such as MMP-13 inhibitors in OA, MMP-14 inhibitors in RA and cancer and MMP-12 inhibitors in COPD, all of which have been proven to be effective in animal models." (PMID 27455234, 2016). "However, we observed that FGFR signaling blockade, in 66c14 carcinoma cells, did not alter significantly expression of EMT and invasion markers, except for MMP-14, confirming the role of FGF family molecules in its regulation." (PMID 22761819, 2012).
infection (29 papers, 2008 to 2025). The state of being infected such as from the introduction of a foreign agent such as serum, vaccine, antigenic substance or organism. "Additionally, multiple MMPs, including MMP-2, MMP-9 and MMP-14, have been implicated in tissue pathology in the lung mucosa and female genital tract during infection through mediating inflammation and ECM degradation." (PMID 35512020, 2022). "A significant increase in the expression of MMP1, MMP3, MMP9, MMP12, MMP13, and MMP14, was noted in Mtb-AG infected, compared with Mtb-SC-infected rabbit lungs, at both 1 and 4 weeks post infection." (PMID 34732811, 2021). "The failure by the recent lineages of Mtb to promote production of MMP14 during active infection might benefit the pathogen by host immune suppression." (PMID 34141493, 2021). "MMP14 was highly expressed only in cells during active infection with the IO lineage." (PMID 34141493, 2021). "MMP14 is a key protein required for leukocyte migration to the site of infection." (PMID 34141493, 2021). "Additionally, MMP14 and several genes in the fibrosis network, which were upregulated by infection, were downregulated to basal (uninfected) levels in response to CC-11050 treatment alone." (PMID 27379099, 2016). "Likewise, matrix metallopeptidase 1 (MMP1), MMP2, and MMP14 were significantly up-regulated while the transcript of MMP11 was repressed by infection." (PMID 27197554, 2016). "Higher collagen deposition after infection in Cyb5r3 SPC–KO mice was accompanied by significantly higher transcript levels of Mmp12, Mmp13, Mmp14, and tissue inhibitor of metalloproteinases 1 (Timp1) but neither Timp2 nor Timp3." (PMID 36749633, 2023). "Neuroinflammation-related neuropeptide Y (NPY), IL-18, and MMP-14 showed distinct changes in the CSF and several brain regions (the prefrontal cortex, PVWM, and hippocampus) 24 h after infection." (PMID 31803186, 2019). "This discovery stems from our previous observation that KSHV-infection of LECs leads to a decrease in PROX1 expression with a concomitant increase in MMP14 expression and MMP14-dependent invasiveness." (PMID 29934628, 2018). "The exact mechanism of action of MMP-14 and its regulation by IV infection in the lung has not yet been described." (PMID 37727782, 2023). "SAT2, DOCK11 and MMP14 were found in both infection and clearance states of Mtb but were not present in control cells." (PMID 34141493, 2021). "Evaluation of the change in MMP14 expression compared to other invadopodia-activated MPPs, MMP2 and MMP9, showed a significant increase in expression of all three MMPs; however, MMP14 showed the highest increase in expression following infection." (PMID 31694343, 2019). "Among them, Cxcl1, Cxcl2, Cxcl3, Cxcl10, IL1b, Socs3, and Mmp14 were overexpressed more than 100-fold compared with the non-infected sample regardless of infection type." (PMID 30858471, 2019). "Infection also induced the expression of co-stimulatory molecules such CD40, CD83, CD86, adhesion molecules (CD38, Itga5, and ICAM1), and tissue invasion molecules such as MMP12 and MMP14." (PMID 22928052, 2012). "Specifically, MMP9, MMP8, and MMP14-proteolysis of IL-8, which is also upregulated in LGMDD2 patients, may lead to an increase in its chemotactic potency by guiding the neutrophils to the site of injury or infection." (PMID 35646913, 2022). "However, MMP-14 only partially affected MUC1 shedding during infection and had no influence on MUC1 shedding in non-infected cells, indicating that other factors are involved in MUC1 release." (PMID 19816567, 2009). "However, there were significant increases in the amount of shed MUC1 following knockdown of MMP-14 at 8 but not 24 h of infection, although no changes were seen following knockdown of ADAM17." (PMID 19816567, 2009).
infection (continued). "Given that MMP14 and CD13 are coexpressed on lung epithelial cells and macrophages, these cells could be the source of sCD13 in the lung, leading to significantly elevated local levels that attract and trap neutrophils and other immune cells in the tissue during infection." (PMID 40168094, 2025). "We observed an increase in the MMP-14 staining in the maternal stroma and caruncular epithelium of Nc-Spain1H placentomes at 10 dpi, whereas MMP-2 and TIMP-2 staining was not apparently modified by the infection (not shown)." (PMID 32552750, 2020).
adenocarcinoma (6 papers, 2006 to 2023). A common cancer characterized by the presence of malignant glandular cells. "Expression of MMP14 by adenocarcinoma cells has been previously established by in situ hybridization, which is consistent with its clustering within the “Adeno 1” cluster." (PMID 17389914, 2007). "Only 53 % of tumors with co-expression of MMP-14 and CD44 were of serous histology versus 72 % in the no/single-expression group; clear cell histology was 16 % versus 8 % in the co-expression group; and unspecified histology was 10 % versus 4 % in the adenocarcinoma group." (PMID 27590006, 2016).
cardiovascular disease (4 papers, 2021 to 2024). "There was a significant association between MMP-2 levels and cardiovascular disease with MMP-14 levels, which is a pro-MMP-2 activator." (PMID 37457745, 2023).
bacterial infection (3 papers, 2015 to 2025). "Analysis of proinflammatory cytokines and chemokines at different time points showed significant upregulation of Tnf, Mmp14, Il1b, Il1a, Il17ra, Cxcl1, Cxcl2, Ccrl2, Ccl3, Ccl4, and Ccl9 after bacterial infection." (PMID 41117166, 2025).
benign tumors (2 papers, 2011 to 2021). "In most studies, malignant and borderline tumours, showed higher MMP-14 expression than benign tumours." (PMID 34344453, 2021). "Few benign tumours, but six borderline tumours showed MMP-14 mRNA expression." (PMID 34344453, 2021).
metabolic disease (2 papers, 2024 to 2025). A congenital disorder (due to inherited enzyme abnormality) or acquired (due to failure of a metabolically important organ) disorder resulting from an abnormal metabolic process. "The overarching aim of the current study was to assess the extent to which suppressing hepatocyte MMP14 gene expression is sufficient to attenuate diet-induced metabolic disease." (PMID 39282008, 2024).
connective tissue disorder (1 paper, 2021). A disease involving the connective tissue. "For instance, Mmp14‐deficient mice exhibit dwarfism and soft tissue fibrosis, conditions sharing some similarities with connective tissue disorders, such as WMS, induced by mutations in FBN genes and other functionally related genes (see Section 1)." (PMID 32730638, 2021).
musculoskeletal disease (1 paper, 2024). "Some of the prominent MMPs involved in musculoskeletal disease are MMP-1, MMP-3, MMP-9, MMP-13, and MMP-14." (PMID 38790904, 2024).
MMP14 also shares sentences with these, for which no sentence is quoted: astrocytomas (4 papers); idiopathic pulmonary fibrosis (4); adenoma (3); adrenocortical carcinoma (3); amyloidosis (3); benign ovarian tumors (3); cutaneous melanoma (3); heart failure (3); multiple sclerosis (3); neurodegenerative disease (3); arteriosclerosis (2); bone sarcoma (2); brain cancer (2); breast (2); chronic kidney disease (2); chronic periodontitis (2); colon adenocarcinoma (2); cyst (2); dwarfism (2); endothelial dysfunction (2); gallbladder carcinoma (2); glaucoma (2); heart disease (2); histiocytoma (2); Hypertension (2); inflammatory bowel disease (2); invasive carcinoma (2); non-Hodgkin lymphoma (2); oligodendroglioma (2); ovarian serous cystadenocarcinoma (2).
A further 130 diseases each share a sentence with MMP14 in 2 papers or fewer.